CRNDE (colorectal neoplasia differentially expressed)
Diseases named in the same sentence as CRNDE in open-access papers (continued):
Sharing a sentence is not in itself a finding about the gene and the disease.
cancer (continued). "The dysregulated expression of several lncRNAs, such as CRNDE, TINCR, and PDIA3P1, has been associated with chemotherapy resistance in several human cancers, highlighting that lncRNAs might represent attractive molecular targets for cancer treatment." (PMID 35717675, 2022). "The biofunction “development of carcinoma” was one of the top cancer-related enriched biofunctions (p-value of 0.0176), with 8 DE lncRNAs: PVT1, CASC2, PCA3, EPB41L4A-AS1, C10orf25, CYTOR, FOXD2-AS1, and CRNDE." (PMID 33926464, 2021). "Among these, XIST, CDKN2B-AS1, CRNDE, TUG1, SOX2-OT, etc. have been reported playing crucial roles in inflammation pathway of cancer progression." (PMID 27809873, 2016). "In addition to our finding that CRNDE is overexpressed and essential for proliferation in RCC, this lncRNA has been demonstrated to support proliferation in many types of cancer cells." (PMID 39091767, 2024). "ENSG00000245694 (also named CRNDE) has been fully investigated in various cancers, however, there was no report for ENSG00000270661 (lncRNA RCAT1)." (PMID 34244473, 2021). "Additionally, Ephrin receptors including EFNA4 belong to tyrosine kinase family, SATB1 and CRNDE have been shown to be elevated in CRC and other cancers, which lead to poor prognosis and metastasis." (PMID 32041340, 2020). "CRNDE has already been identified as regulating metabolic pathways in cancer, but its role in diseases other than cancer has not been established." (PMID 31863035, 2019). "In fact, CRNDE has been shown to be upregulated in numerous types of cancers, but the molecular mechanism of CRNDE in the regulation of cancer progression was not clear." (PMID 28086904, 2017). "In addition, siRNA-mediated silencing of all transcripts of eight genes that showed a consistent differential splicing signature across multiple cancer types (ABCC5, ANKHD1, DYNLL1, F8, RPL31, TMEM14C, UQCC, and CRNDE) failed to reveal differences in cell viability." (PMID 25424858, 2015).
tumor (38 papers, 2012 to 2026). "We also noted that some proliferation-associated genes in tumor cells were also significantly regulated by CRNDE knockdown, including IGFBP4, ANXA1, KLF6, AATF, and IFI16." (PMID 33298855, 2020). "Animal experiments revealed that CRNDE gene knockout markedly inhibited HB tumor growth and angiogenesis." (PMID 38390281, 2024). "It has been shown that CRNDE overexpression can promote M2 polarization of TAMs and induce tumor angiogenesis." (PMID 37325064, 2023). "CRNDE has been shown to act as an oncogene promoting tumor proliferation, invasion, migration, and drug resistance in multiple cancer types, including HCC." (PMID 35999564, 2022). "Our study found that the expression of mir-9-5p differed between the tumor and normal groups, and it can also be targeted and regulated by CRNDE genes." (PMID 33767729, 2021). "CRNDE, an oncogene that is usually overexpressed in tumor cells, contributes a lot to cellular proliferation, migration, invasion, and apoptosis." (PMID 32471511, 2020). "PCNA staining showed that CRNDE knockdown obviously reduced the proportion of proliferating (PCNA+) tumor cells." (PMID 28178668, 2017). "Additionally, CRNDE expression was positively correlated to tumor immunity, stromal activation (pan-F-TBRS, EMT1-3, angiogenesis, etc.), cell cycle progression, and DNA damage repair in TCGA LGG samples." (PMID 37194105, 2023). "In summary, we have uncovered a novel mechanism by which CRNDE mediates tumor growth and sorafenib resistance via interactions with p300 that may offer effective treatment avenues to combat sorafenib resistance in HCC." (PMID 35999564, 2022). "In addition, CRNDE is also overexpressed in a variety of other tumor cells such as melanoma and lymphocytic leukemia cells." (PMID 26231038, 2015). "Furthermore, the CRNDE mRNA was up-regulated in tumor samples compared with normal tissues." (PMID 38822362, 2024). "Results showed that the regulatory factors CRNDE, EDN1, JUNB, and MAP2K1/2, ZFP36 mainly regulate differentially expressed genes (VEGFA, EGFR, PLAUR) to regulate invasion of cells, invasion of tumor, and microtubule dynamics." (PMID 38711992, 2024). "We investigated how the expression levels of CRNDE, FREM2, and SPRY1 genes were connected with the “old” and “new” tumor types." (PMID 36613601, 2022). "The results indicated that the expression levels CRNDE and CYTOR were significantly correlated (p < 0.05) with tumour grade, age (<40 and ≥40 years), PRS type, 1p19q chromosome codeletion, IDH mutation status and chemotherapy status." (PMID 35359593, 2022). "To investigate the potential biological functions of CRNDE in HCC development, we first examined its expression levels in HCC tumor tissues and the corresponding adjacent tissues (n = 47)." (PMID 32826865, 2020). "In GSE45436, SNHG11, CRNDE, MYLK‐AS1, E2F3, and CHEK1 were highly expressed in the tumor group, while RASGEF1B was the opposite, which were consistent with the results of TCGA." (PMID 33232580, 2020). "CRNDE (Colorectal Neoplasia Differentially Expressed) and HOTAIR, for example, are upregulated in neoplastic tumor tissue and in the blood of CRC patients." (PMID 28573140, 2017). "Therefore, the present study suggests that NCAPD3-knockdown-induced differentially expressed genes (DEGs) such as CRNDE, EDN1, and JUNB can regulate cell and tumor invasion through EGFR and PLAUR." (PMID 38711992, 2024). "Given the importance of CRNDE in CRC, in the present study we investigated that CRNDE expression was remarkably upregulated in CRC tissues and that CRNDE overexpression was positively correlated with advanced pathological stages and larger tumor sizes." (PMID 28796262, 2017). "Moreover, we applied in vitro and in vivo methods to reveal the involvement of CRNDE in CRC tumorigenesis, as a tumor promoter and as a facilitator of CRC growth and metastasis." (PMID 28594403, 2017).
tumor (continued). "In this paper, we report that lncRNA CRNDE expression was remarkably upregulated in CRC tissues and that lncRNA CRNDE overexpression was positively correlated with advanced pathological stages and larger tumor sizes." (PMID 28796262, 2017). "Firstly, we selected several genes related to tumor metastasis through the NCBI database and literature, including SRA1, DBF4 zinc finger B (DBF4B), ZNFX1 antisense RNA 1 (ZFAS1), colorectal neoplasia differentially expressed (CRNDE), endoplasmic reticulum lectin (OS9), and others." (PMID 34011971, 2021). "Further, to determine whether CRNDE participates in regulating miR-29b-3p expression, we investigated expressions of CRNDE and miR-29b-3p in paired CRC resected tumor tissues and corresponding adjacent non-tumor tissues obtained from a public GEO dataset (GSE32323)." (PMID 34680556, 2021).
CRNDE also shares sentences with these, for which no sentence is quoted: chronic myelogenous leukemia (2 papers); pancreatic cancer (2); uveal melanoma (2); acute lymphoblastic leukemia (1); adenocarcinoma (1); astrocytomas (1); atherosclerosis (1); bladder cancer (1); breast tumors (1); COVID-19 (1); esophageal squamous cell carcinoma (1); infarction (1); Insulin resistance (1); invasive breast carcinoma (1); kidney disease (1); lymph node metastasis (1); multiple myeloma (1); Obesity (1); oligoastrocytoma (1); oligodendroglioma (1); osteosarcoma (1); papillary carcinomas of the breast (1); papillary renal cell carcinoma (1); pneumonia (1); type 2 diabetes (1).